INS (insulin)
Diseases named in the same sentence as INS in open-access papers (continued):
Sharing a sentence is not in itself a finding about the gene and the disease.
Obesity (continued). "At the same time, mounting evidence suggests that intestinal flora can regulate insulin synthesis and secretion, affect androgen metabolism and follicular development, and is involved in the occurrence of chronic inflammation and obesity." (PMID 36967808, 2023). "There are several antidiabetic reports of chlorogenic and caffeic acids used as novel insulin sensitizers; they improve glucose tolerance, insulin resistance, and cellular oxidative stress and manage obesity." (PMID 37138848, 2023). "Many previous studies have shown that L. reuteri is an important probiotic that can control weight and obesity, improve insulin sensitivity and glucose homeostasis, increase gut integrity and immune regulation, and reduce liver disease." (PMID 38020719, 2023). "The clinical and paraclinical findings have determined the close link between obesity the occurrence of metabolic alterations, such as high blood pressure and reduced sensitivity to insulin, decreased glucose tolerance and dyslipidemia." (PMID 38248733, 2023). "Six-week-old male LIPTER(Tg) and WT mice were fed a HFD (45 kcal% fat) to induce obesity, insulin resistance and cardiac abnormalities as previously reported 40,41." (PMID 37264180, 2023). "Leptin prevents obesity by reducing hunger, promoting satiety, increasing insulin sensitivity and lipolysis, whereas, it protects against cognitive decline by preventing neurodegeneration and obesity-induced leptin resistance." (PMID 37363537, 2023). "As such, postprandial insulin responses and/or hyperlipidemia following a standardised nutrient challenge (high-fat or mixed meal) may offer a useful metric by which to identify individuals with dysfunctional adipose tissue and at a high risk of obesity-related disease progression." (PMID 37402955, 2023). "Potentiation of leptin and insulin signaling in POMC neurons confers protection against diet-induced obesity by increased WAT browning and decreased adiposity." (PMID 37443835, 2023). "In humans, the PR diet considerably improved physical parameters, blood glucose and lipid levels, energy expenditure, and insulin sensitivity in patients suffering from obesity and MetS." (PMID 36776765, 2023). "Similar findings of increased oxidative stress susceptibility with PON2 deficiency have been reported in numerous disease models, including atherosclerosis, heart failure, impaired hepatic insulin signaling, and obesity." (PMID 37891899, 2023). "It was proposed that obesity, insulin dysregulation, and laminitis are elements of this clinical disorder syndrome." (PMID 37628596, 2023). "A disruption of the gut microbiota has been shown to contribute to obesity by influencing glucose/lipid tolerance and insulin resistance and promoting low-grade inflammation in the gut." (PMID 38022013, 2023). "Acute hyperinsulinemia can cause blood vessel dilation by releasing nitric oxide, but this process is impaired in insulin-resistant individuals with obesity or hypertension." (PMID 37416924, 2023). "In this regard, changes in insulin levels/sensitivity in patients with obesity correlated with DNA methylation in the promoter of the leptin gene." (PMID 36674935, 2023). "This species also has various beneficial functions, such as preventing obesity, increasing insulin sensitivity, and promoting the production of acetate to protect against nonalcoholic steatohepatitis development." (PMID 36673515, 2023). "Exercise can help reduce the risk of death from endometrial cancer by reducing the rates of obesity and by regulating lipoproteins, insulin resistance, and endogenous sex hormone concentrations." (PMID 37958310, 2023). "Increased inflammation in adipose tissue, a consequence of obesity, results in changes in adipokine secretion patterns and the release of pro-inflammatory cytokines, leading to insulin resistance rises in tissues with active metabolism." (PMID 37835451, 2023).
Obesity (continued). "In particular, the increased circulating levels of insulin, related to obesity, seem to stimulate ovarian production of androgens, which are in turn aromatized to estrogen in adipose tissue." (PMID 37542617, 2023). "In individuals living with obesity, the adipose tissue is responsive to the lipolytic effect of catecholamines and relatively insensitive to the anti-lipolytic effect of insulin (“adipose tissue IR”)." (PMID 36980074, 2023). "Beyond the influence on insulin sensitivity of different tissues and organs through complex mechanisms, autophagy can also be affected by inflammation in obesity." (PMID 37152942, 2023). "This study shows how the principles of the two seemingly conflicting models of obesity (the “energy balance model” and the “carbohydrate insulin model”) can be valid, and it will help in progressing towards a unified model of obesity." (PMID 37479702, 2023). "We also assessed a range of secondary efficacy indicators after the 28-day treatment, including lipid levels, fasting glucose levels and insulin, inflammatory cytokines, and obesity parameters." (PMID 37828034, 2023). "Obesity causes extracellular matrix (ECM) remodelling which can develop into serious pathology and fibrosis, having metabolic effects in insulin-sensitive tissues." (PMID 37383542, 2023). "Earlier reports show that metabolically healthier and insulin sensitive individuals with obesity have lower levels of pro-inflammatory mediators and lower plasma FFA levels." (PMID 38026205, 2023). "Several studies have suggested that there is association between the SNPs rs3200401 and rs217727, and the etiological mechanisms of obesity, such as insulin dysregulation, and abnormal lipid and glucose metabolism." (PMID 37104004, 2023). "Both SREBP-1 mRNA and its active nuclear protein are increased in ob/ob mouse livers; in double mutant Lepob/ob × Srebp-1−/− mice, hepatic steatosis was markedly attenuated, but obesity and insulin resistance remained persistent." (PMID 37047048, 2023). "Anti-MIF significantly improved whole-body and adipose insulin sensitivity and attenuated obesity in PD group." (PMID 37283810, 2023). "Here, in an experimental model, we demonstrated HFD-induced obesity, glucose intolerance, and reduced insulin sensitivity, as well as abnormal serum lipid and inflammatory factor levels." (PMID 37762143, 2023). "When miR-29 was suppressed, mice showed higher early-onset food intake, late-onset obesity, increased insulin resistance, and hypertrophy of adipocytes, while simultaneous deletion of Nras remarkably attenuated this phenotype." (PMID 38003013, 2023). "Several dietary flavonoids improve insulin sensitivity, inhibit obesity-related oxidative stress, improve the redox balance in affected individuals and thus improve macronutrient metabolism." (PMID 37252233, 2023). "Previous studies have found that gut flora can influence cognitive behavior by affecting insulin sensitivity and inflammatory pathways; gut flora also affects obesity in the same ways." (PMID 37249983, 2023). "In patients with obesity and T2D, short-term aerobic exercise increased peripheral insulin sensitivity more than hepatic insulin sensitivity and thus enhanced whole-body insulin action." (PMID 37109347, 2023). "Low testosterone in men is associated with these comorbidities and several studies have demonstrated the beneficial effects of TTh on insulin sensitivity, parameters of obesity and inflammation." (PMID 37148486, 2023). "Collectively, these data delineate that the supplementation of EPA entirely mediates the insulin tolerance and obesity-induced inflammation in UCP1 and in a temperature-independent manner." (PMID 37240054, 2023). "The concentration of the free-fatty-acid palmitate in the circulation of the children with obesity appeared to influence the insulin levels with accentuated hyperinsulinemia in pre-pubertal subjects with high palmitate levels." (PMID 37623862, 2023).
Obesity (continued). "Among obesity-related biomarkers, insulin was the most strongly correlated to body adiposity indices in both sexes and strength of these correlations generally decreased with age." (PMID 36859451, 2023). "It was positively associated with obesity class III and fat mass in grams (p < 0.001 for both), severe SLD (p < 0.001) and insulin sensitivity (p < 0.001 for both parameters)." (PMID 37834412, 2023). "Altered amino acid profiles in the obesity condition are often accompanied by concomitant changes in the resistance and secretion of insulin." (PMID 37485499, 2023). "In contrast, decreased testosterone concentration in individuals with hypogonadism leads to obesity, decreased insulin sensitivity, and dyslipidemia, which is corrected by testosterone administration." (PMID 37384220, 2023). "HFD‐fed SSTR5 KO mice exhibited lower HOMA‐IR than HFD‐fed WT mice at similar BW levels, indicating that SSTR5 deletion maintains insulin sensitivity even under HFD‐induced obesity." (PMID 36585794, 2023). "As a result, mice were more prone to obesity, exhibiting a decrease in energy expenditure, impaired glucose tolerance, insulin and leptin resistance, and increased food intake." (PMID 37582706, 2023). "APLN encodes a peptide hormone secreted by adipocytes, involved in the regulation of various metabolic functions and upregulated by insulin and obesity." (PMID 36978128, 2023). "In vivo, beverage consumption showed a reduction of blood glucose, increase of insulin tolerance, improvement of lipid profile, control of obesity, and reduction of oxidative stress." (PMID 38069300, 2023). "By blocking CB1R, it was shown that obesity-induced insulin and leptin resistance, as well as glucose homeostasis, was improved in obese and overweight animals with metabolic syndrome." (PMID 37371762, 2023). "A previously published meta-analysis assessed the associations between exercise training and changes in IR, fasting glucose, and fasting insulin in children and adolescents with overweight or obesity." (PMID 37635963, 2023). "Barchetta recently examined the relationship between the SPISE index and various insulin sensitivity indicators in children with overweight/obesity." (PMID 36677025, 2023). "Obesity contributes to AT remodeling and a pro‐inflammatory and insulin‐resistant state, which contributes to ectopic lipid deposition, increased hepatic de novo lipogenesis, excess VAT accumulation, and altered SAT TG turnover." (PMID 38036455, 2023). "The ability to metabolize the naturally occurring FXR antagonist, tauro-β-muricholic acid, is the basic process leading to obesity, steatosis, and impaired glucose, insulin, and leptin tolerance." (PMID 37513500, 2023). "Once more, it has been demonstrated that obesity and excess energy intake shift the balance of mitochondrial dynamics and metabolic deterioration, leading to insulin resistance." (PMID 38026693, 2023). "PRKCB deficiency reduces the obesity syndrome of mice, while RAB3A is involved in the regulation of insulin secretion." (PMID 37620670, 2023). "The main finding of the present study is that the severity of sleep apnea is independently associated with adipose tissue insulin sensitivity as determined by percentage FFA suppression, in individuals with obesity and new diagnosis of OSA." (PMID 39434962, 2023). "For example, the dual GIP and GLP-1 RA tirzepatide at 5-15 mg was shown to be superior to basal insulin and to 1 mg of semaglutide weekly in reducing levels of hemoglobin A1c (HbA1c) and body weight in patients with overweight or obesity and T2D." (PMID 37703084, 2023). "Patients with obesity also have higher insulin levels, leading to increased IGF-1 in breast cancer cells, which activates the PI3K/AKT/mTOR and RAS/RAF/MAPK signaling pathways that result in endocrine therapy resistance." (PMID 37173991, 2023).
Obesity (continued). "Decreased insulin production by pancreatic beta cells and peripheral insulin resistance that occur later in the disease course has a vital role in obesity." (PMID 37456411, 2023). "Its role in regulating the sensitivity to insulin has been proposed, but in obesity, it can exacerbate an insulin resistance." (PMID 36674022, 2023). "After sleeve gastrectomy, rats with diet-induced obesity exhibited reduced markers of adiposity (body weight, whole-body adiposity and the adipokine leptin) as well as an improved insulin sensitivity." (PMID 37274331, 2023). "Obesity and insulin dysregulation/resistance are often grouped under one term, even though a clear distinction should be made between them, as obesity does not necessarily result in ID, and both can exist without the other." (PMID 37152686, 2023). "We observed a causal effect of NAFLD on fasting insulin levels, which was consistent with a previous MR study, but not fasting glucose levels using genetic instruments for NAFLD excluding one obesity-related SNP (rs2068834)." (PMID 36800955, 2023). "Linked to enhanced energetic efficiency, endurance training in individuals with obesity and T2D has also been shown to decrease diacylglycerol, total ceramides, and Cer14:0 content in skeletal muscle with a positive correlation with insulin sensitivity." (PMID 36904216, 2023). "The mechanisms behind the impact of obesity on insulin levels can be related to a decrease in total and high affinity insulin receptors, thus requiring increased insulin secretion." (PMID 36520252, 2023). "Improved glycemic and lipid control were observed in patients with obesity, whose insulin levels during OGTT were lowered following metformin treatment." (PMID 37623862, 2023). "Studies have confirmed a significant increase in CRP and insulin concentrations in the saliva of children with obesity." (PMID 36831972, 2023). "PAHSA levels in serum are positively correlated with insulin sensitivity while their levels in breast milk negatively correlate with obesity in nursing mothers." (PMID 36923222, 2023). "NAFLD is an important complication of obesity, and the liver is one of the insulin-targeted tissues." (PMID 37537674, 2023). "The biomarkers used to characterize the TPDM6315 extracts in this study possess anti-inflammatory, anti-obesity, and improved insulin-resistant properties." (PMID 37367060, 2023). "Overall, MOTS-c prevented HFD-induced obesity through increased energy expenditure, improved glucose utilization and insulin sensitivity." (PMID 36670507, 2023). "Mounting evidence revealed that vitamin B12 and folate supplementation improved obesity and insulin sensitivity in T2D." (PMID 37755259, 2023). "This is in addition to its well- recognized insulin-sparing and sensitizing action, which is inherent in obesity and T2DM." (PMID 36830898, 2023). "TNF-α signalling can alter a broad range of metabolic pathways and affect insulin sensitivity in obesity." (PMID 37033938, 2023). "Therefore, further exploration of body parameters with important effects on insulin sensitivity may deepen our understanding of the relationship between obesity and NAFLD risk and provide new insights into the study of risk factors and pathogenic mechanisms of lean NAFLD." (PMID 36742435, 2023). "Several studies have shown negative correlations between BMI and absolute IGF-1 levels, while others reported increased circulating IGF-1 in obesity and, specifically, abdominal obesity due to elevated portal insulin levels." (PMID 37571382, 2023). "Lowering the PAI-1 concentration seems to be promising for lowering IR in patients with obesity by improving insulin sensitivity in adipose tissue." (PMID 37371961, 2023). "Despite its action in improving insulin sensitivity and appetite inhibition, patients with obesity present greater serum levels of this hormone than lean individuals." (PMID 36831188, 2023).
Obesity (continued). "Further support came later when we administered HFCS to mice lacking KHK and found that it provided even more protection from obesity, fatty liver and insulin resistance, with about one-quarter of the effect from the glucose–insulin pathway." (PMID 37482773, 2023). "Fetal malnutrition and early exposure to endocrine-disrupting compounds also contribute to obesity and impaired insulin secretion and/or sensitivity." (PMID 37274345, 2023). "Knockout of KLK7 in AT dampened obesity-induced AT inflammation and preserved insulin sensitivity in mice." (PMID 37152954, 2023). "Clinical heterogeneity exists in overall obesity and abdominal obesity in terms of insulin secretion and sensitivity." (PMID 36909323, 2023). "Previously, butanoic acid has been reported to exert anti-obesity properties by improving fasting glycemia, reducing body weight, enhancing insulin tolerance, and improving energy metabolism in animal models." (PMID 37999401, 2023). "IR, a state in which insulin effector organs become less responsive to insulin, is highly correlated with obesity." (PMID 37305058, 2023). "Quinic acid derivatives have demonstrated promising effects in the treatment of glycemic control, obesity, and dyslipidemia, as well as insulin secretion, among others." (PMID 37760813, 2023). "In a previous study, a physiological increase in cardiac catalase activity levels in mitochondria due to obesity was able to limit H2O2 levels while maintaining normal insulin responsiveness in cardiac tissue." (PMID 37238003, 2023). "In mice, ablation of NLRP3 prevented the obesity-induced inflammasome activation in fat depots and liver together with enhanced insulin-signaling." (PMID 36817440, 2023). "A clinical study reported that obesity blunts the insulin mediated microvascular recruitment in forearm muscle." (PMID 37014444, 2023). "L. plantarum dfa1 effectively attenuated prediabetes and obesity despite only a subtle impact on the gut microbiota, which implies a possible impact on insulin resistance." (PMID 36986190, 2023). "Reducing dietary BCAA intake rapidly reduced diet-induced obesity, improved glucose tolerance, reversed fatty acyl-coA accumulation in skeletal muscle, normalized glycine content, and improved skeletal muscle insulin sensitivity." (PMID 38027178, 2023). "With time, insufficient insulin secretion, glucolipotoxicity, and obesity-related inflammation, result in hyperglycaemia and, finally, T2D." (PMID 36996012, 2023). "In other studies, circulating serum levels of insulin-sensitizing adiponectin have been found to be lower in obesity, so future therapeutic tools will need to be developed to increase concentrations, and therefore, promote a healthier phenotype." (PMID 37239098, 2023). "In mice with obesity-associated diabetes, leptin downregulation leads to overexpression of RAGE in β-cells and therefore inhibits insulin infusion and mediates AGE-elicited pancreatic islet apoptosis." (PMID 37446161, 2023). "Recent studies in skeletal muscle, adipose tissue, and liver explored the association between obesity-induced ECM remodelling, integrin signalling, and insulin resistance." (PMID 37383542, 2023). "In obesity, the expansion of fat reserves induces the dysfunction of endocrine factors, resulting in the metabolic alteration of insulin in the target tissues and in the pancreatic β-cells." (PMID 38136211, 2023). "Abnormal body fat accumulation in obesity can promote the development of other diseases such as T2D, characterized by pancreatic β-cells dysfunction and insulin resistance in target organs." (PMID 36904281, 2023). "As such, a similar severity of prediabetes was demonstrated between glucose and fructose obesity by fasting blood glucose, fructose, and insulin, together with an oral glucose tolerance test and the HOMA index (see method)." (PMID 36986190, 2023).